ALB (albumin)
Diseases named in the same sentence as ALB in open-access papers (continued):
Sharing a sentence is not in itself a finding about the gene and the disease.
cancer (continued). "In addition, studies have shown that the integration of these biochemical indicators such as the modified Glasgow Prognosis Score (mGPS), C-reactive protein to albumin ratio (CAR), and neutrophil to lymphocyte ratio (NLR) can effectively improve the accuracy of cancer prognosis prediction." (PMID 34150609, 2021). "In cancer patients, serum albumin level is often normal or only slightly decreased in the early stages of cancer but drops as the disease progresses, and low serum albumin levels have been found to provide negative prognostic significance in cancer patients." (PMID 34885242, 2021). "However, no further research explored the mechanism of albumin in relation to cancer in the human body." (PMID 34041866, 2021). "The prognostic value of the CRP to albumin ratio (CAR) among older adults with cancer is not known." (PMID 34830936, 2021). "However, studies on cachectic adult cancer patients with low plasma albumin concentrations have reported a negative effect on transdermal absorption of fentanyl." (PMID 33371493, 2020). "Previous meta-analyses of cancer patients indicated that several ratios of pretreatment systemic inflammatory markers or/and nutritional markers, such as the neutrophil-lymphocyte ratio (NLR), the albumin-globulin ratio (AGR), and the C-reactive protein-albumin ratio (CAR), can predict prognosis." (PMID 31931816, 2020). "The clinical biochemistry-based indexes, such as prognostic nutritional index (PNI), albumin-to-alkaline phosphatase ratio (AAPR), albumin/globulin ratio (AGR), albumin (ALB), serum urea nitrogen (BUN) and creatinine (CREA) have been considered as independent prognostic factors for many cancers." (PMID 32211311, 2020). "Hence, higher values of the CRP/albumin ratio in the CRP pointed to a relatively lower protein status in cancer cachexia albeit albumin concentrations were not below the reference value." (PMID 32083092, 2020). "As amino acids are orders of magnitude more abundant in plasma in protein as compared to free form, the macropinocytic scavenging of albumin, the most abundant plasma protein, is one important strategy that promotes the growth of cancer cells when blood is not in abundant supply." (PMID 30967004, 2019). "Therefore, micro-formulations based on hydrophobic interactions between RF and human serum albumin (HSA) may apply to overcome this limiting factor and to increase the therapeutic efficiency of the RF photosensitizer in cancer therapy." (PMID 30934597, 2019). "ALI was developed to assess systemic Inflammation and cancer cachexia based on patients’ body mass index (BMI), serum albumin concentration and neutrophil-to-lymphocyte ratio (NLR) from the time of diagnosis in patients with metastatic non-small-cell lung cancer (NSCLC) to detect cancer progression." (PMID 31819103, 2019). "Could markedly deranged values of C-reactive protein and s-albumin, such as found in this study, signal a relatively short remaining survival time in patients with incurable cancer and no clinical signs of ongoing infection?" (PMID 29534089, 2018). "Hence, albumin which coated chitosan-based NPs with negative charges gets these coated NPs in repulsion with cell membranes of both normal and cancer cells." (PMID 29545617, 2018). "However, comorbidities, performance status, cancer cell type, severity score, and serum albumin levels were not related to the survival of NIPPV therapy." (PMID 29329356, 2018). "More recently, a novel combination model of CRP and albumin—CRP/Alb ratio—has also been increasingly appreciated since it could serve as a predictor of a clinical outcome in patients with serious infectious disease and those with cancers." (PMID 28676731, 2017). "Thus, the cumulative effect of both ALB and GLB may provide good prognostic value for cancer patients." (PMID 28654895, 2017).
cancer (continued). "By combining the albumin and globulin indicators in a single measurement, AGR more accurately reflects the body's nutritional and inflammatory states and may be particularly useful as an outcome indicator for cancer patients." (PMID 28187463, 2017). "Albumin also exhibits exotic activities, such as glucuronidase activity (for instance, (S)-carprofen glucuronide—an NSAID—hydrolysis mediated by tyrosine and lysine residues), and enolase activity; the latter is highly important for differential diagnosis of benign and malignant tumors." (PMID 28718803, 2017). "In addition to the responses to SCQ1 and SCQ3, other significant determinants in the HD group (groups B+C) were, age, education, employment, presence of an informal care-giver, history of malignancy, global cognition scores, TMTB scores and Albumin<30g/L (surrogate of physical illness)." (PMID 25992775, 2015). "Thus, unlike the situation in normal tissues where albumin returns from the extracellular fluid to the plasma via lymphatic drainage, once in cancer extracellular fluid, albumin is trapped and does not re-enter circulation." (PMID 25193858, 2014). "Here we showed that human cancer cells, HepG2 and U2OS, cultured in medium containing BCAAs with Fischer's ratio about 3, which was shown to have highest activities to synthesize and secrete of albumin, had higher activities to induce premature senescence and elevate mTORC1 activities." (PMID 24223226, 2013). "If albumin and IgG, both of which do not bind galectin-1, are excluded, galectin-1 binds approximately 10–15% of the remaining glycoproteins in healthy sera and up to 40% in cancer sera." (PMID 22028908, 2011). "The mechanism by which a low serum albumin might impact on relapse-free, cancer-specific and overall survival is not clear." (PMID 17375036, 2007). "However, we observed that the high CCR group showed elevated levels of weight, albumin, hemoglobin (HGB), and BMI, which are all correlated with nutritional status, suggesting that CCR levels may offer some indication of nutritional status in cancer patients." (PMID 41195263, 2025). "However, there are no UK guidelines attributing low albumin levels to specific cancer sites." (PMID 40941010, 2025). "Additionally, numerous connections exist between cancer and nutritional indicators, such as albumin (ALB) and prognostic nutritional index (PNI), reflecting the nutritional and immunological status of the body and thereby impacting the clinical outcomes of cancer patients." (PMID 38956686, 2024). "This indicates that albumin may predict survival in patients with cancer regardless of cancer type." (PMID 37880704, 2023). "This strategy could help LFU20 to insert into the hydrophobic cavity of albumin to form an LFU20/albumin complex, which facilitates LFU20 accumulation in tumors by the enhanced permeability and retention effect, and internalization into the lysosomes of cancer cells." (PMID 36393853, 2022). "However, whether there are associations between appetite and albumin, or between appetite and CRP, that differ between men and women has not previously been studied in a palliative cancer population." (PMID 35629338, 2022). "However, serum albumin could be used to assess the nutritional status and negative nitrogen balance in malnourished patients with cancer." (PMID 36718344, 2022). "Similar to peripheral blood-based biomarkers derived from blood count, albumin levels are significantly affected by inflammatory pressure, and lower albumin levels are seen in cases of chronic inflammatory disorders and cancer as a negative acute phase reactant." (PMID 36533070, 2022). "Besides these factors, univariate analyses showed that AMI with cancer patients had significantly lower levels of albumin, T.chol, and LDL-c than those without cancer, which seemed to be caused by deterioration of nutrition status, which were different from traditional coronary risk factors." (PMID 34444823, 2021).
cancer (continued). "Biochemical thresholds that reflect low-grade inflammation, serum CRP >10mg/L and low serum albumin concentrations <35 g/L, combined in the Glasgow Prognostic Score (GPS) remained independently prognostic for patients without an underlying diagnosis of cancer at 6-months post diagnosis of acute PE." (PMID 34962922, 2021). "In cancer patients, it has been reported that a low albumin level is related to serious blood toxicity as well as non-blood toxicity with chemotherapy, and that a low albumin level may be a factor indicative of a poor prognosis." (PMID 30607523, 2019). "However, both serum albumin and globulin levels are easily influenced by non-cancer-related factors, including dehydration and edema, which can weaken their efficiency and accuracy in predicting the prognosis of cancer patients." (PMID 29300750, 2018). "In subgroup analysis for patients without malignancy disease, the relative risk for mortality was also associated with APACHE II score (hazard ratio (HR) = 1.04, 95% CI = 1.03–1.06, p < 0.001) and CRP/albumin ratio (HR = 1.39, 95% CI = 1.02–1.90, p = 0.04 for high CRP/albumin ratio)." (PMID 30297655, 2018). "Therefore, it is thought that albumin/globulin ratio (AGR), which is reflecting both the systemic inflammatory response and the systemic nutritional status, may be important prognostic factor in predicting clinical outcomes and survival of the cancer patients." (PMID 29757575, 2018). "Therefore, a low albumin to globulin ratio (AGR) may amplify the predictive power of these two elements and serve as a more robust predictor of an enhanced inflammatory and adverse survival in cancer patients." (PMID 26966671, 2016). "Moreover, chemotherapeutics may remain high residue and high toxicity in the blood stream because of lacking of albumin to bind to the drugs and this may also contribute to cancer mortality." (PMID 26656866, 2015). "When the age cutoff was changed from 80 to 60 years, age was associated with cancer in bivariate (P≤.002) and multivariable analysis (P≤.002), and the negative predictive value of this model with 3 variables (age >60 y, ALP, and albumin level) increased to 95% when all tests were negative." (PMID 24762986, 2014). "Biochemical parameters, such as C-reactive protein and albumin (combined to form the modified Glasgow Prognostic Score, mGPS), alkaline phosphatase (Alk phos), γ-glutamyl transferase (GGT) and serum calcium have been reported to be associated with cancer and non-cancer mortality." (PMID 20717110, 2010). "The basis of the observation that albumin had independent prognostic value is not clear but it may be that chronic illness, reflected by a lower albumin, also impacts on cancer survival." (PMID 18797461, 2008). "Particularly, relationships between AFP, ALB, CA125, and RBC, LYM, PCT, and TBIL values play an important role in distinguishing between cancer and non-cancer cases." (PMID 40943960, 2025). "Instead, it is thought that the biomarker combination formed by values such as ALB, ALP, PCT, and LYM collectively contributes to keeping the patient in the “No Cancer” class." (PMID 40943960, 2025). "For instance, blood serum levels of alkaline phosphatase (ALP) and albumin (Alb) are not tumor biomarkers, but their ratio (ALP to Alb ratio, APAR) can be useful in predicting a patients’ prognosis for a variety of cancer types." (PMID 39064013, 2024). "Multivariate analysis showed that DMB-related ONJ was significantly more common in patients with malignant tumors, with a short duration of ARA administration, low serum albumin levels, and no osteolysis." (PMID 39036251, 2024). "Additionally, the reliance on serum albumin and PNI as primary markers of nutritional status may not capture the full spectrum of nutritional deficiencies, particularly in patients with complex cancer-related conditions." (PMID 39529928, 2024).
cancer (continued). "GPS is a clinical scoring system for cancer patients, defined by two liver-derived acute-phase proteins (APPs), C-reactive protein (CRP; positive APP) and albumin (negative APP)." (PMID 37803016, 2023). "However, many believe that the hyposerum albuminemia seen in patients with advanced cancer may be more related to the systemic inflammatory response, and therefore, it is more recommended to consider serum albumin as an indicator of inflammation rather than nutrition in the CONUT score." (PMID 37668711, 2023). "The “lactated Ringer versus Albumin in early Sepsis theraPy” (RASP) trial compared 4% albumin solution and lactated Ringer’s in septic cancer patients, finding no significant mortality differences at 7 or 28 days." (PMID 38139434, 2023). "The mean level of serum albumin, TP, and Hgb had a negative statistically significant linear correlation with mean level of SGA score in adult patients with cancer." (PMID 36869395, 2023). "And as expected, adjustment for age did not alter the fact that ΔS-Cys-Albumin was significantly higher in K2EDTA plasma relative to serum and LiHep plasma in matched collections from the cancer-free control patients." (PMID 36182099, 2022). "This is a retrospective study comparing albumin levels and neutrophil-to-lymphocyte ratio (NLR) of patients with long-standing CD who underwent small bowel resection with and without malignancy." (PMID 36449698, 2022). "Furthermore, compound scores created by mixing albumin levels with positive acute reactants like CRP, as in the Glasgow prognostic score or globulin in albumin-globulin ratio, could also aid in prognosis estimations in patients with cancer and should be thoroughly investigated." (PMID 36533070, 2022). "Since abnormal ALB and ALP can result from various non-cancer situations, and thus AAPR is not a cancer-specific biomarker." (PMID 34539891, 2021). "Patients with cancer or infections present commonly increased CRP values, but not decrease albumin value." (PMID 32344777, 2020). "Compared with the noncancer group, the cancer group had a higher FFA level (0.45 vs 0.41 mmol/L, P < 0.001) and a higher albumin level (42.41 vs 40.56 mmol/L, P < 0.001)." (PMID 31773260, 2020). "Characteristics of cancer patients meeting the criteria CRP ≥ 0.5 mg/dL; plasma albumin <3.2 g/dL; hemoglobin <12 g/dL; or none of the criteria." (PMID 32850383, 2020). "However, the natural history of serum calcium and albumin is exceptionally well-studied in population-based cohorts, including the Janus and the Norwegian Oslo Health Study cohorts, which provided clear predictions for expected values among women without cancer." (PMID 32723677, 2020). "Thereby, nanoparticles have been obtained by coupling human serum albumin (HSA), a non-toxic carrier of weakly soluble drugs and folic acid (FA) a cancer-targeting ligand." (PMID 31835371, 2019). "However, in addition to identifying mutations in oncogenes and tumor suppressor genes, TCGA identified frequent mutations in albumin (ALB) and apolipoprotein B (APOB), which are not frequently mutated in other cancer types, suggesting that they may play unique roles in the development of HCC." (PMID 30429453, 2018). "If cancer patients can balance such a high TER with an increased lymphatic return, we cannot see why this would not be possible also for septic patients after an initial albumin leakage." (PMID 40057738, 2025). "Cancer patients have chronically increased Interleukin-6 (IL-6) in the circulating blood, affecting the acute-phase proteins (APPs); positive APP corresponds to CRP, and negative APP to albumin." (PMID 35204642, 2022). "Furthermore, several studies have also suggested that albumin, total cholesterol, NLR and LMR hold no prognostic value for certain groups of cancer patients." (PMID 35388133, 2022).
cancer (continued). "have demonstrated that the inflammatory state of a body at the baseline is an important negative prognostic biomarker in cancer cachexia patients, and ALI is a comprehensive index of BMI, albumin, neutrophils, and lymphocytes, thus reflecting systemic inflammation." (PMID 35898878, 2022). "In summary, a novel and simple scoring system by integrating sALB with serum ALP, named albumin-to-alkaline phosphatase ratio (AAPR), has been constantly validated as a reliable prognostic indicator across a wide range of malignant tumors, regardless of their treatment options." (PMID 34746006, 2021). "In cell culture, binding of KP1019 or NKP-1339 to albumin leads to a decrease in activity, as no EPR effect can be observed and conditions in vitro are therefore probably less favorable for protein-mediated uptake into cancer cells." (PMID 26988975, 2016). "However, the GPS was derived from the prognostic data from cancer patients, and the cutoff values established based on their H-CRP and albumin levels may not be the most appropriate for patients with AMI." (PMID 34270463, 2021). "Normal hepatocytesafter FACS (NHaF) and cancer cells after FACS (CAaF) were transplanted into two spots onopposite sides of the backs of nude mice; and also into the spleens of three groups (NHaF,CAaF and controls) of non-albumin rats (NARs), from which we measured blood albumin levels,using ELISA." (PMID 35111514, 2020). "CRP is one of the most frequently used serum markers to assess cancer prognosis, but due to lack of specificity, several studies have been reported, including Glasgow Prognostic Score (Glasgow Prognostic Score (GPS) and CRP/albumin ratio (CAR), which combine CRP and albumin." (PMID 32676164, 2020). "While looking at all the well performed and published data available, proofing the role of CRP, albumin, GPS, mGPS, and C/A ratio as prognostic factor for many different cancers, we can only speculate why we could not find significance concerning OS and DFS in our collective." (PMID 28740506, 2017).